EGFR (epidermal growth factor receptor)
Diseases named in the same sentence as EGFR in open-access papers (continued):
Sharing a sentence is not in itself a finding about the gene and the disease.
non-small cell lung carcinoma (continued). "The clinical presentation of epidermal growth factor receptor (EGFR)-mutant non-small-cell lung cancer (NSCLC) in DS was reported and literature on the subject reviewed." (PMID 28903458, 2017). "Their aim was to detect mutated epidermal growth factor receptor (EGFR), the biomarker of non-small cell lung cancers (NSCLCs)." (PMID 28902169, 2017). "Appearance of EGFR tyrosine kinase receptor inhibitors (TKI)had brought a revolutionary change in non-small cell lung cancer(NSCLC), such as gefitinib, erlotinib, afatinib and AZD9291, especially those with adenocarcinomas." (PMID 28160565, 2017). "The treatment of EGFR exon 19-deleted and exon 21 L858R-substituted non-small-cell lung cancer (NSCLC) is through tyrosine kinase inhibitor (TKI)." (PMID 29201462, 2017). "In non-small cell lung cancer (NSCLC) a low frequency subclone with MET amplification was selected for during treatment with EGFR tyrosine kinase inhibitors (TKI), allowing for development of a resistant MET- amplified tumour." (PMID 28716075, 2017). "Similar results are seen for other mutation-targeted agents including epidermal growth factor receptor (EGFR) inhibitors in non-small cell lung cancer (NSCLC), BRAF inhibitors in melanoma, and HER2 inhibition in breast cancer." (PMID 28056859, 2017). "Epidermal growth factor receptor (EGFR) T790M mutation accounted for over half of drug resistance cases in EGFR-mutant non-small cell lung cancer (NSCLC) patients treated with EGFR tyrosine kinase inhibitors (TKIs) and led to different outcomes." (PMID 29245913, 2017). "The epidermal growth factor receptor (EGFR) is an established target for anti-cancer treatment in non-small cell lung cancer (NSCLC)." (PMID 28416737, 2017). "AZD9291 has been shown to have a response rate (RR) of 61 % in EGFR T790M-positive non-small cell lung cancer (NSCLC) patients." (PMID 27448564, 2016). "Targeted therapy offers a more promising outcome in advanced non-small cell lung cancer (NSCLC), but only patients who harbor driving mutations such as epidermal growth factor receptor (EGFR) potentially benefit." (PMID 27893413, 2016). "In contrast, three KRAS- or EGFR-driven non-small cell lung cancer (NSCLC) cell lines treated with TGFβ or erlotinib to induce EMT displayed reduced glycolysis to oxidation ratio and lower PDK4 expression." (PMID 27777765, 2016). "EGFR-TKIs, such as erlotinib and gefitinib, are commonly used for the treatment of non-small cell lung cancer (NSCLC)." (PMID 27455225, 2016). "To improve the clinical utility of cfDNA, we developed a sensitive peptide nucleic acid (PNA)-based method for analyzing EGFR and KRAS mutations in the plasma cfDNA of patients with advanced non-small cell lung cancer (NSCLC)." (PMID 27519791, 2016). "Epidermal growth factor receptor (EGFR)-targeted tyrosine kinase inhibitors (TKIs) have emerged as first-line drugs for non-small cell lung cancers (NSCLCs)." (PMID 27285768, 2016). "EGFR-mutant non-small cell lung cancer is routinely treated with EGFR inhibitors, although resistance inevitably develops." (PMID 27283993, 2016). "The model was parametrized using experimental and clinical pharmacokinetic data to investigate potential combinations of the HAP evofosfamide with the targeted tyrosine kinase inhibitor erlotinib against EGFR-activated non small cell lung cancer." (PMID 27560187, 2016). "For example, c-MET amplification or activation has been reported as one of the major mechanisms for developing resistance to EGFR tyrosine kinase inhibitor (TKI) treatment in non-small cell lung cancer (NSCLC) patients." (PMID 27923392, 2016). "Here we employ CAPP-Seq ctDNA analysis to study resistance mechanisms in 43 non-small cell lung cancer (NSCLC) patients treated with the third-generation epidermal growth factor receptor (EGFR) inhibitor rociletinib." (PMID 27283993, 2016).
non-small cell lung carcinoma (continued). "The transforming EML4-ALK fusion transcript was initially detected in approximately 7% of patients with non-small-cell lung cancer (NSCLC), with the fusion being mutually exclusive with the better-known EGFR mutations." (PMID 27105842, 2016). "For example, in non-small cell lung cancer (NSCLC), administration of EGFR tyrosine kinase inhibitors (EGFR TKI) have shown high efficiency in the EGFR mutated subpopulation and have led to improved progression-free and overall survival." (PMID 27548442, 2016). "In particular, EGFR testing on liquid biopsy for patients with non-small-cell lung carcinoma (NSCLC) has been approved in Europe based on the results of the IFUM trial that showed an acceptable sensitivity and specificity of this approach." (PMID 27448974, 2016). "EGFR inhibition-based therapies are currently in use for a wide variety of solid malignancies including non-small cell lung cancer, breast cancer, and prostate cancer." (PMID 26918609, 2016). "Soluble isoforms of EGFR (sEGFR) have also been identified in conditioned media of breast, non-small cell lung cancer and pancreatic cancer cells as well as circulating in bloodstream." (PMID 27152724, 2016). "Taken together, our study has implied that inhibition of SREBP-driven lipogenic program combined with EGFR TKIs is a promising therapeutic strategy for non-small cell lung cancer." (PMID 27447558, 2016). "The heregulin-dependent HER2-HER3 heterodimer was reported to be the most oncogenic HER dimer, and this dimer induced resistance of colorectal cancer to anti-EGFR antibodies and of non-small cell lung cancer to EGFR tyrosine kinase inhibitors." (PMID 27768588, 2016). "MET gene amplification ranging from frequencies of 1-20% has been documented in a variety of human cancers, including liver metastases from colon carcinoma, non-small cell lung carcinomas with acquired resistance to EGFR inhibitors and gastric cancers." (PMID 26879245, 2016). "Met receptor is a promising therapeutic target in multiple cancer types, especially non-small cell lung cancer, in which Met overexpression has recently been shown to contribute to EGFR TKI resistance, including resistance to gefitinib and erlotinib." (PMID 27716616, 2016). "We develop this framework in the specific context of EGFR-driven non-small cell lung cancer, which is commonly treated with the tyrosine kinase inhibitor erlotinib." (PMID 27560187, 2016). "One hundred and ninety-one patients given erlotinib or gefitinib for EGFR-mutant non-small cell lung cancer were identified." (PMID 27907909, 2016). "EGFR gene is involved in a wide variety of malignancies such as non-small cell lung cancer, colon cancer and head-and-neck squamous cell carcinoma." (PMID 27013591, 2016). "Mutation of this receptor has been shown to play a crucial role in the response of non-small cell lung carcinoma (NSCLC) to EGFR-targeted therapies." (PMID 27552105, 2016). "This is further supported by a similar study of non-small cell lung cancer where suppression or inhibition of MUC1 reduced EGFR signaling." (PMID 27092881, 2016). "Erlotinib is a tyrosine kinase inhibitor commonly used to treat EGFR-mutant non-small cell lung cancer." (PMID 27560187, 2016). "These drugs are effective for treating advanced EGFR mutation-positive non-small cell lung cancer (NSCLC), especially in patients who harbor EGFR exon 21 L858R mutation (EGFRL858R) or exon 19 deletions (EGFRdel19)." (PMID 27912760, 2016). "Many studies have suggested that genetic polymorphisms in the epidermal growth factor receptor (EGFR) are associated with risk of glioma, breast cancer, colorectal adenoma and colorectal cancer, and non-small cell lung cancer." (PMID 27437777, 2016).
non-small cell lung carcinoma (continued). "The inhibition of epidermal growth factor receptor (EGFR) signaling by Gefitinib provides a promising treatment strategy for non-small cell lung cancer (NSCLC); however, drug resistance to Gefitinib and other tyrosine kinase inhibitors presents a major issue." (PMID 27283902, 2016). "Tyrosine kinase inhibitors (TKIs) against the human epidermal growth factor receptor (EGFR) are now standard treatment in the clinic for patients with advanced EGFR mutant non-small-cell lung cancer (NSCLC)." (PMID 28149837, 2016). "Human cancer cell lines A431 (EGFR overexpressing, epidermoid), A549 and H441 (both EGFR medium expressing, non-small cell lung cancer) were xenografted in mice." (PMID 27602494, 2016). "For example, the EGFR kinase inhibitors gefitinib and erlotinib for non-small cell lung cancer patients; the EGFR/ERBB2 inhibitor lapatinib for ERBB2-positive breast cancer patients, and the VEGFR kinase inhibitor sorafenib for patients with renal cancer." (PMID 26751490, 2016). "First-generation epidermal growth factor receptor tyrosine-kinase inhibitors (EGFR-TKI) including geiftinib and erlotinib have been the standard first-line treatment for metastatic non-small-cell lung cancer (NSCLC) harboring activating EGFR mutation." (PMID 26911310, 2016). "The co-occurrence of epidermal growth factor receptor (EGFR) mutations and anaplastic lymphoma kinase (ALK) rearrangements constitutes a rare molecular subtype of non-small-cell lung cancer (NSCLC)." (PMID 27533086, 2016). "For example, in non-small cell lung cancers (NSCLCs), several of the critical signalling pathways are solely controlled by EGFR." (PMID 26916442, 2016). "The epidermal growth factor receptor (EGFR) tyrosine kinase inhibitor (TKI) erlotinib has been approved based on the clinical benefit in non-small cell lung cancer (NSCLC) patients over the past decade." (PMID 26575584, 2016). "It is interesting to note that 25-hydroxyvitamin D3 activates vitamin D receptor target gene expression and suppresses EGFR mutant non-small cell lung cancer growth." (PMID 27513329, 2016). "The principal mutations of EGFR, ALK, KRAS, BRAF, PIK3CA and HER2 were analyzed in 44 patients with non-small-cell lung cancer." (PMID 26968843, 2016). "This study investigated the relationship between the inhibitor of differentiation 1 (ID1) and non-small cell lung cancer EGFR-TKI resistance in vivo and in vitro to determine any statistical significance and discuss the underlying mechanism." (PMID 27978873, 2016). "The aim of this meta-analysis is to evaluate the clinical efficacy and safety of intercalated combination of chemotherapy and EGFR-TKIs versus chemotherapy alone in the first-line therapy of advanced non-small cell lung cancer (NSCLC)." (PMID 27978869, 2016). "The over-expression of EGFR has been observed in many solid tumors, such as colon, ovarian, breast and non-small cell lung cancer (NSCLC)." (PMID 27527130, 2016). "Frequency of EGFR testing and receipt of erlotinib among non-small cell lung cancer patients diagnosed in 2010 overall and by tumor stage, Patterns of Care." (PMID 27294665, 2016). "EGFR-expressing CTCs have also been detected in metastatic breast cancer patients as well as patients with non-small-cell lung cancers." (PMID 27643613, 2016). "The exception is in EGFR mutant non-small cell lung cancers treated with a tyrosine kinase inhibitor." (PMID 26848525, 2016). "Chemotherapy with platinum compounds and gemcitabine is frequently used in first-line treatment of advanced non-small cell lung cancer (NSCLC) patients in which tyrosine kinase inhibitors (EGFR or ALK) cannot be administered." (PMID 26650486, 2016). "Epithelial-mesenchymal transition (EMT) is one mechanism of acquired resistance to inhibitors of the epidermal growth factor receptor-tyrosine kinases (EGFR-TKIs) in non-small cell lung cancer (NSCLC)." (PMID 26789630, 2016).
non-small cell lung carcinoma (continued). "A number of such targets have been identified, including the mutant EGFR in non-small cell lung cancer, a receptor we have shown to constitutively enter the endocytic recycling pathway." (PMID 26859680, 2016). "The epidermal growth factor receptor (EGFR) is highly expressed in cancer cells, including non-small-cell lung cancer (NSCLC)." (PMID 27268079, 2016). "For example, the drug gefitinib (DB00317) is sensitive to the G719A/C variation in the EGFR gene of patients suffering from non-small cell lung cancer." (PMID 27801815, 2016). "miR-146a suppresses cell growth, induces cellular apoptosis and inhibits epidermal growth factor receptor downstream signaling in five non-small cell lung cancer cells." (PMID 26418898, 2016). "Ever since, particular benefits from targeting EGFR have been observed for patients with advanced non-small cell lung cancer (NSCLC)." (PMID 27486382, 2016). "Mutant EGFR expressing tumors, including non-small cell lung cancer (NSCLC), are treated with the tyrosine kinase inhibitors erlotinib and gefitinib." (PMID 27602494, 2016). "Our findings correspond to results from a previous study where coactivation of EGFR and an opioid receptor in non-small cell lung cancer has been observed." (PMID 26788073, 2016). "Although cranial radiotherapy is considered the standard treatment for brain metastasis (BM), EGFR tyrosine kinase inhibitors (TKIs) have shown promising activity in EGFR mutant non-small cell lung cancer (NSCLC) patients with BM." (PMID 27447711, 2016). "MiR-128b was shown to be a direct negative regulator of EGFR in non-small-cell lung cancer (NSCLC) cell lines." (PMID 26646588, 2016). "The tyrosine kinase inhibitors (TKI) against epidermal growth factor receptor (EGFR) are widely used in patients with non-small cell lung cancer (NSCLC)." (PMID 27071706, 2016). "Elevated HGF expression and c-MET amplification have been linked with acquired resistance to epidermal growth factor receptor tyrosine kinase inhibitors (EGFR TKIs) in patients with non-small cell lung cancer (NSCLC)." (PMID 27422720, 2016). "Two small molecule EGFR tyrosine kinase inhibitors (EGFR-TKIs; gefitinib and erlotinib) are approved for the treatment of advanced non-small cell lung cancer (NSCLC) in the first-line setting in patients whose tumors harbor an activating EGFR mutation." (PMID 27036206, 2016). "A clinical trial of MetMab combined with the epidermal growth factor receptor (EGFR) kinase inhibitor erlotinib to block metastasis in non-small cell lung cancer was recently halted in Phase 3, but other clinical trials with MetMab are expected." (PMID 27766096, 2016). "Avitinib is the first China-developed novel EGFR inhibitor that has entered in global clinical trials, and will provide a precision targeted therapy for non-small cell lung cancer patients." (PMID 26152224, 2015). "Rapid and dramatic responses have been observed with oncogene-directed treatments, such as BRAF inhibitors in melanoma and epidermal growth factor receptor (EGFR) inhibitors in non-small cell lung cancer." (PMID 25682878, 2015). "Similar to our results with PDT, nimotuzumab has shown to selectively enhance anti-tumor effects of ionizing radiation of non-small-cell lung carcinoma (NSCLC) cell lines with high EGFR expression." (PMID 25918252, 2015). "In this study we successfully applied an EGFR FISH classification previously developed for non-small cell lung cancer, for use in esophageal cancer and characterised a series of 160 FFPE samples using dual colour probe EGFR FISH." (PMID 26478746, 2015). "Subsequently, understanding the correlation between a mutation in the epidermal growth factor receptor (EGFR) gene and the response to gefitinib improved treatment strategies for advanced non-small cell lung cancer (NSCLC)." (PMID 25941796, 2015).
non-small cell lung carcinoma (continued). "In the past decade, the advancement on the treatment targeting mutated Epidermal Growth Factor Receptor (EGFR) and Anaplastic Lymphoma Kinase (ALK) have changed considerably the possibility of therapy for Non Small Cell Lung Cancer (NSCLC) patients." (PMID 26422230, 2015). "In non-small cell lung cancer cell lines, the inhibitory effect of Nimotuzumab on EGFR signaling was found to be dependent on the cell surface expression of EGFR but not the status of EGFR mutation." (PMID 25886314, 2015). "The strategies to effectively inhibit EGFR signaling pathway have been used in non-small cell lung cancer (NSCLC) targeted therapy." (PMID 26706953, 2015). "EGFR is overexpressed in various cancers, including non-small cell lung cancer, colorectal cancer, pancreatic cancer, esophagogastric cancer and gastric cancer as well." (PMID 26538117, 2015). "In non-small cell lung cancer, EGFR inhibitor- resistant gefitinib-treated and the (sensitive) CL-387,785-treated H1975 cells were compared to identify transcriptional changes with EGFR-activating mutations." (PMID 26005638, 2015). "Noteworthy, sensitivity to gefitinib could be restored in an EGFR-mutated non-small cell lung carcinoma (NSCLC) cell line by the inhibition of the HGF/c-Met axis." (PMID 26729094, 2015). "FISH for EGFR copy number alterations has been most extensively studied in formalin fixed paraffin embedded (FFPE) non-small cell lung cancer samples." (PMID 26478746, 2015). "Mutations in the tyrosine kinase domain of epidermal growth factor receptor 1 (EGFR) occur in ~10–40% non-small cell lung cancers (NSCLC), with the highest incidence in patients of Asian descent." (PMID 25969993, 2015). "In non-small cell lung carcinoma (NSCLC), 70% of patients with Epidermal Growth Factor Receptor (EGFR) activating mutations will have a favorable initial response to EGFR inhibitors gefitinib or erlotinib." (PMID 26000702, 2015). "Interstitial lung disease (ILD) occurs in patients with non-small cell lung cancer receiving EGFR inhibitors." (PMID 26288223, 2015). "Epidermal growth factor receptor (EGFR) tyrosine kinase inhibitors, such as gefitinib and erlotinib, are oral molecule-targeted drugs for non-small cell lung cancer." (PMID 26288223, 2015). "Other authors reported that GRP can induce Akt phosphorylation at Serine 473 in a non-small cell lung carcinoma cell line, and that this activation occurred through transactivation of the epidermal growth factor receptor (EGFR), a known Akt activator." (PMID 26097883, 2015). "Epidermal growth factor receptor tyrosine kinase inhibitor (EGFR-TKI) has been used for the first-line treatment of non-small cell lung cancer (NSCLC) and has shown good clinical effects." (PMID 25800570, 2015). "Second, a few reports have described cases in which EGFR-mutant non-small-cell lung carcinoma has acquired resistance to EGFR-TKI therapy through transformation to small cell lung cancer." (PMID 25861509, 2015). "For non-small cell lung cancer (NSCLC), the effectiveness of TKIs is dependent on the mutational status of epidermal growth factor receptor (EGFR)." (PMID 25853020, 2015). "The aim of this study was to explore the role of long non-coding RNA UCA1 (urothelial cancer-associated 1) in acquired resistance to epidermal growth factor receptor tyrosine kinase inhibitors (EGFR-TKIs) in EGFR-mutant non-small cell lung cancer (NSCLC)." (PMID 26160838, 2015). "Current, there is a phase II study of afatinib as third-line treatment for patients in Korea with stage IIIB/IV non-small cell lung cancer harboring wild-type EGFR." (PMID 25537503, 2015). "The introduction of tyrosine kinase inhibitors antagonizing overactivated or amplified EGFR has strikingly expanded the therapeutic armamentarium in non-small cell lung cancer." (PMID 26675484, 2015).